RN7SL317P (RNA, 7SL, cytoplasmic 317, pseudogene)
Gene: Miscellaneous RNA gene on chromosome 19 (53,629,713 to 53,630,041, forward strand). Ensembl gene ENSG00000242668.
Homologues: Orthologues: chimpanzee Metazoa_SRP (96% identical). Paralogues in human: RN7SL33P (77% identical), RN7SL526P (74% identical), RN7SL40P (73% identical), Metazoa_SRP (72% identical), Metazoa_SRP (71% identical), RN7SL487P (71% identical), RN7SL775P (71% identical), RN7SL156P (67% identical), RN7SL1 (66% identical), RN7SL2 (66% identical), RN7SL733P (66% identical), RN7SL248P (65% identical), and 696 more.